VCAN (versican)
Diseases named in the same sentence as VCAN in open-access papers (continued):
Sharing a sentence is not in itself a finding about the gene and the disease.
tumor (305 papers, 2007 to 2026). "For example, the cancer-associated fibroblast regulator NNMT, CD163, a marker of tumor-associated macrophages (TAMs), and oncogenic proteoglycan VCAN were significantly upregulated from the NFT stroma to the invasive stroma." (PMID 41233595, 2026). "We first assessed the association between stromal VCAN expression and tumor cell-intrinsic cGAS–STING expression in CRC." (PMID 40451897, 2025). "Our analysis revealed that although VCAN was downregulated in tumor tissues, it paradoxically emerged as a prognostic risk factor for PCa." (PMID 40365288, 2025). "Versican is a protein abundant in many cancers that has been associated with the infiltration of CD8+ tumor-infiltrating lymphocytes." (PMID 40361362, 2025). "It has also been recently demonstrated that the accumulation of VCAN is strongly associated with an influx of tumor-associated macrophages, an immunosuppressive immune cell population." (PMID 40361362, 2025). "The VCAN G3 domain is implicated directly in angiogenesis, with tumor cells expressing a G3 construct showing increased expression of fibronectin and VEGFA, and the ability to increase EC proliferation and migration." (PMID 40623650, 2025). "Although ADAMTS-9 has been linked to VCAN proteolysis in various contexts, including embryogenesis and cardiac and aortic anomalies, its role in the tumor microenvironment remains underexplored." (PMID 39682243, 2024). "The ECM has been associated with impacting T-cell infiltration toward the tumor and in this article we have identified VCAN and its structural modification, chondroitin sulfate as having a key role in T-cell invasion." (PMID 38517140, 2024). "Tumor cells have been reported to produce VCAN as part of the pericellular matrices that associated with tumor cell invasion and smooth muscle cell migration." (PMID 38517140, 2024). "Mechanistically, versican-deficient tumours in mice are less aggressive and have fewer macrophages and neutrophils." (PMID 38791926, 2024). "This group concluded that VCAN was associated with poor prognosis through induction of tumor development by reducing TNF-mediated cellular apoptosis." (PMID 38957320, 2024). "Apart from the tumour itself, VCAN also regulates the proliferation of crucial components associated with tumours." (PMID 38791985, 2024). "VCAN is found in various sources in cancer, including tumor cells, tumor-associated stroma, and tumor-associated immune cells." (PMID 37108649, 2023). "Researchers established a conditional knockout mouse model of the host VCAN and observed that the loss of VCAN in mice promoted tumor cell proliferation, followed by angiogenesis." (PMID 37217855, 2023). "Versican was shown to be overexpressed in a variety of proliferative cancers as well as tumor-associated stroma in several studies." (PMID 37259101, 2023). "Taken together, these data indicate that VCAN secreted by cancer cells triggers IKKβ-mediated NF-κB activation in tumor-associated macrophages and promotes metastasis." (PMID 36980752, 2023). "In accordance with its anti-adhesive properties and, thus, the facilitation of cell migration, an elevated level of versican has often been associated with a more invasive tumor phenotype." (PMID 36831399, 2023). "It has been shown that versican can be present in at least four different sources in the tumor microenvironment, including cancer cells, tumor-associated myeloid cells, tumor-infiltrating lymphocytes, and stromal cells." (PMID 37259101, 2023). "VCAN protein expression was positively associated with tumor invasion (P = 0.011) and HER2 overexpression (P = 0.031)." (PMID 36842141, 2023). "VCAN protein expression was significantly positively associated with tumor invasion depth (P = 0.011) and HER2 protein expression (P = 0.031)." (PMID 36842141, 2023). "VCAN expression has also been identified as a diagnostic and therapeutic target in colon cancer and as a potential biomarker of the tumor microenvironment." (PMID 37108649, 2023).
tumor (continued). "A similar analysis for VCAN revealed the strongest signal in tumor-associated activated stellate cells and secondmost in tumor transformed epithelial cells." (PMID 36923282, 2022). "One study found that in versican-deficient tumours, pleural T regulatory cell numbers were reduced along with tumour mass in a preclinical model of mesothelioma." (PMID 34527586, 2021). "In summary, targeting versican, and in particular targeting specific structural forms of versican can maximise the therapeutic potential whilst minimizing deleterious effects that can be associated with tumour matrisome targeting." (PMID 34527586, 2021). "The overexpression of VCAN in cancer has also been reported to be associated with tumor progression." (PMID 33604385, 2021). "In our own work, we found versican was a member of a signature of twenty-two matrisome molecules that associated with tumour tissue stiffness at both the gene and protein levels." (PMID 34527586, 2021). "Elevated levels of versican in the tumour are mostly expressed by either malignant cells and/or tumour-associated stromal cells." (PMID 34527586, 2021). "To confirm the stable overexpression of IRF9 and the associated target gene VCAN, we isolated RNA from tumor homogenate." (PMID 33430083, 2021). "As a large extracellular matrix proteoglycan, VCAN regulated proliferation, invasion, and metastasis adhesion in a vast majority of tumor cells, and VCAN expression was associated with poor prognosis in most cancers." (PMID 33200655, 2020). "Versican and tumor-associated macrophages (TAMs) have a synergistic effect on BC growth and metastasis." (PMID 32847060, 2020). "Versican expression in mice, identified in late stages of tumor progression, was associated to a high number of peri-tumoral infiltrating TAMs." (PMID 31334111, 2019). "In tumour cell lines, versican overexpression was associated with increased cell migration and tumour stage." (PMID 29207682, 2017). "The EGFR signaling has been demonstrated to contribute to the enhancement of BCSC self-renewal induced by versican or by tumor-associated macrophages." (PMID 29100291, 2017). "We demonstrated that in all the tumors investigated, versican of host (i.e., stromal origin) was distributed in the tumor periphery and associated with the tumor vasculature and its connective tissue that invades the tumor." (PMID 29222454, 2017). "A high prevalence of fibroglandular breast tissue can lead to increased accumulation of versican, a proteoglycan associated with high tumor grade and invasive disease in patients with high breast densities and mammographic MCs." (PMID 25896922, 2015). "Versican, a large chondroitin sulfate proteoglycan, which is more frequently expressed in malignant tumors and is implicated in tumor progression, has been shown to activate macrophages." (PMID 25125485, 2014). "Versican staining in epithelial cells was associated with several clinicopathological factors, including tumor size (P = 0.002), mucinous differentiation (P = 0.001), and histological grade (P = 0.01)." (PMID 22711178, 2013). "Through interactions with ECM molecules, versican regulates many cellular processes of adhesion, migration, proliferation, apoptosis, and angiogenesis, all events implicated in tumor progression and metastasis." (PMID 24212952, 2011). "Elevated expression of versican both in tumor stroma and in cancer cells is frequently associated with poor outcome in breast, brain, ovary, and prostate cancers, sarcoma, and mesothelioma." (PMID 24212952, 2011). "The over-expression of versican was also significantly associated with the elevated expression of ERα and PR in tumor cells, higher tumor grade and invasiveness." (PMID 21791066, 2011). "To understand how versican modulates signaling pathways associated with tumor metastasis, we examined expression of versican V1 isoform (250–300 kDa) and the related molecules in different cell lines known to possess different capacities in tumor metastasis." (PMID 21079779, 2010).
tumor (continued). "The direct expression of versican by tumor cells is variable with a greater expression being associated with highly malignant tumors." (PMID 17662123, 2007). "Previous studies have shown that VCAN may be associated with M1 macrophage polarization in the tumour microenvironment." (PMID 40386063, 2025). "Notably, tumor spheroids showed increased expression of proteins associated with solid tumor progression, such as versican and MMPs." (PMID 40098313, 2025). "This suggests that VCAN can indeed affect the polarization of tumour-associated macrophages." (PMID 40386063, 2025). "Moreover, the inhibition of VCAN amplifies the anti-tumour effectiveness of endostatin by mitigating the induced accumulation of myeloid-derived suppressor cells (MDSCs), tumour-associated macrophages (TAMs), and inflammatory cytokines within the TME." (PMID 38791985, 2024). "VCAN is associated with tumor growth and metastasis, including in GC." (PMID 39040110, 2024). "Furthermore, TGFβ1 has been shown to promote versican secretion from stromal cells, while stromal accumulation of versican in tumours has been associated with increased inflammation." (PMID 38948119, 2024). "Many studies have shown that VCAN has anti-adhesive properties, the ability to modulate proliferation, cell migration, and angiogenesis, and is associated with the invasiveness potential of malignant tumors, thereby contributing to tumor progression." (PMID 39682243, 2024). "CHST11 may be important in tumor-associated VCAN sulfation patterns, especially in early stromal changes." (PMID 39098880, 2024). "This difference in initial tumor volume may be due to the fact that the LTR10.XRCC4 knockout also reduced expression of VCAN, a gene that is often associated with tumor growth and establishment." (PMID 39018396, 2024). "Our analysis reveals that CD8+ T-cell contact with tumor associates with the location of VCAN expression, the specific glycovariant of VCAN [defined through the pattern of posttranslational attachments of glycosaminoglycans (GAG)], and the cell types that produce the variant." (PMID 38517140, 2024). "Also, among the hub genes of the NAT, SN, and SNAT lists, COL1A2 (12%), KRAS (14%), and VCAN (9%) have a higher mutation rate in tumour samples, respectively." (PMID 37118990, 2023). "Importantly, we show that tumor-secreted versican causes IKKβ activation in myeloid cells to foster this pro-inflammatory circuitry." (PMID 36980752, 2023). "The results position these cancers as favorable candidates for anti-IL-1β therapy, and versican as a diagnostic and prognostic biomarker, as well as a therapeutic target in this tumor category that comprises 9% of all human cancers, alone or in combination with anti-IL-1β agents." (PMID 36980752, 2023). "We found that VCAN+ tumour-associated macrophages (TAMs) might undergo M2-like polarization and differentiate in the tumour region." (PMID 37383234, 2023). "Versican silencing improved the antitumor efficacy of endostatin by alleviating its induced accumulation of myeloid-derived suppressor cells (MDSCs), tumor-associated macrophages (TAMs) and inflammatory cytokines in the tumor microenvironment." (PMID 36203562, 2022). "Versican has also been associated with the progression of tumor processes." (PMID 33804223, 2021). "Additionally, glioma-derived versican has been suggested to promote tumor expansion by stimulating Toll-like receptor 2 signaling in tumor-associated macrophages." (PMID 34944101, 2021). "There are, however, significant differences between PTMmut and overall mutations, with e.g., hornerin (HRNR, a paralog of FLG) being a top-10 PTMmut gene in 14/31 tumor types and versican (VCAN), collagen III (COL3A1) and XIV (COL14A1) all mutated in 9/31 tumor types." (PMID 33802493, 2021). "VCAN is secreted by the fibroblasts of the tumor-associated stroma and by cancer cells." (PMID 29747682, 2018). "Increased stromal VCAN is associated with a decrease in tumor-infiltrating CTLs." (PMID 29970158, 2018).
tumor (continued). "Next, we investigated whether lumican or versican expression was associated with one of the tumor-progression chromosome CNAs, i.e. gain of chromosome 8q, 13q, or 20q." (PMID 28481899, 2017). "Finally, we observed changes in the phenotype of tumor-associated adipocytes compared to non tumor associated adipocytes; and evaluated with immunohistochemistry versican, adiponectin, Adipo R1, CD44, and perilipin expression in hATT and hATN slides." (PMID 28173833, 2017). "However, the spatial and causal relationship between versican, versican cleavage and tumor angiogenesis remains incompletely understood." (PMID 29222454, 2017). "Previously, we suggested that the interaction between versican and human epidermal growth factor receptors may be directly associated with tumor aggressiveness." (PMID 27490467, 2016). "Vcan encodes the proteoglycan Versican that stimulates angiogenesis and can promote tumor growth." (PMID 25260591, 2014). "Versican gene expression is linked to mesenchymal to epithelial transition in cell culture experiments and the proteoglycan induces mesenchymal to epithelial transition of metastatic tumor cells accelerating their proliferation." (PMID 23405249, 2013). "Similarly, the expression of versican is significantly associated with higher expression of ERα (P < 0.01) and PR (P < 0.01) in tumor cells only in patients with MAMCs." (PMID 21791066, 2011). "Consequently, the proteolysis of VCAN and associated factors may be valuable indicators of tumor progression." (PMID 39682243, 2024). "Thus, versican seems to have the ability to specifically direct the inflammatory monocyte response, conceivably correlated to the differential recruitment of lymphocytes, and differentiation into tumor-associated macrophages and dendritic cells (DC)." (PMID 31068944, 2019). "The cell-derived xenograft model study in nude mice showed that knockdown of VCAN in tumour cells significantly suppressed tumour size." (PMID 40386063, 2025). "Reduction of VCAN expression in mice can attenuate tumor angiogenesis, and transfection of tumor cells with the V2 isoform results in extensive tumor vasculature." (PMID 40623650, 2025). "We then sought to understand the relationship between the proteoglycan versican and the receptors CD44 and the EGFR family, which are expressed on the membrane of carcinomatous cells and identified as key mediators linking versican to tumor cells." (PMID 40005948, 2025). "Available tumor sections were evaluated for versican and versikine expression, versican proteolysis status (VPP), PD‐L1 CPS, and CD8 + T‐cell infiltration." (PMID 39757733, 2025). "We also detected the expression of VCAN in tumour samples from BCC patients and verified that VCAN expression was significantly higher in BCC than in normal skin tissue." (PMID 40386063, 2025). "Versican (VCAN) and LAMC1, which are strongly associated with tumor progression and increased metastasis risk, were identified only in CRLM-SD, whereas TIMP3 and decorin, which are linked to an opposing effect in cancer, were found exclusively in CRLM-CA." (PMID 40617497, 2025). "Quantification of VCAN proteolysis was restricted to the tumor stroma, and it relies on the detection of the neoepitope αDPEAAE, which is formed upon proteolytic cleavage by ADAMTS proteases." (PMID 40361362, 2025). "To verify the relationship between VCAN and M1 macrophage polarization, we performed fluorescence staining of tumour sections from cell-derived xenograft mouse models." (PMID 40386063, 2025). "Versican immunoreactivity was found to be less intense in areas adjacent to in situ carcinomatous regions compared to invasive regions, which exhibited extensive and strong staining, suggesting a direct relationship between versican and tumor invasiveness." (PMID 40005948, 2025). "This, in turn, contributes to tumor progression by modifying chondroitin sulfate and promoting VCAN upregulation." (PMID 40507957, 2025).